MTOR (mechanistic target of rapamycin kinase)
Diseases named in the same sentence as MTOR in open-access papers (continued):
Sharing a sentence is not in itself a finding about the gene and the disease.
Hyperglycemia (continued). "In summary, high EVOO intake with diet decreases the likelihood of cancer and increases life expectancy because EVOO can counteract DMBA and TFA-induced damage by improving global DNA methylation pattern, while decreasing hyperglycemia, mTOR activity, and inducing SIRT1 function among other." (PMID 35215560, 2022). "Side effects of mTOR-inhibiting therapies include severe infections as well as aplasia syndromes like anemia and thrombopenia and metabolic side effects such as hyperlipidemia and hyperglycemia." (PMID 35845058, 2022). "Hence, the AKT/PI3K/mTOR pathway has been reported to be strongly impaired in STZ-induced hyperglycemia and inflammation in Wistar rats." (PMID 35327652, 2022). "In addition, hyperglycemia is reported in nearly all kinds of PI3K/AKT/mTOR inhibitors but only in two CDK4/6 inhibitors (palbociclib and dalpiciclib)." (PMID 36091147, 2022). "Additionally, hyperglycemia directly activates the mTOR pathway which negatively regulates autophagy." (PMID 36476132, 2022). "The findings suggest that LF may regulate tumor progression during hyperglycemia by regulating the NT5DC3/PI3K/AKT/mTOR signaling pathway." (PMID 36553697, 2022). "Thus, activation of the mTOR pathway in the retina of STZ-induced diabetic mice is likely to be in response to hyperglycemia-induced GLUT1 upregulation leading to the increased glucose uptake." (PMID 33637094, 2021). "However, in the rat model, the authors observed a decline in the AKT activity, while our study showed an upregulation of the p-AKT/p-mTOR pathway after 16 weeks of hyperglycemia." (PMID 35046899, 2021). "At this point, we hypothesized that the mTOR signaling pathway may be the link between the factors related to hyperglycemia and autophagy, consequently leading to the neuronal cell loss in DR." (PMID 33637094, 2021). "The most common grade III treatment related AEs were Fatigue (27%), Anorexia (11%) and Oral Mucositis (8%) which were managed by administration of standard treatment modalities Hyperglycemia which has been previously reported in mTOR regimens was observed in one patient." (PMID 33935721, 2021). "In addition, the drug has an ability to decrease the level of the mammalian target of rapamycin [mTOR] protein and reverse the effect of hyperglycemia on the activity of Madin -Derby Canine Kidney cells (MDCK cells)." (PMID 33562458, 2021). "Other side effects seen with mTOR inhibitors include metabolic derangements such as hyperglycemia and hyperlipidemia, which mandate close monitoring of blood glucose and lipid profile routinely while on everolimus and utilization of anti-hyperglycemic agents and statins for the biochemical control." (PMID 32751138, 2020). "Our results also showed that acute hyperglycemia could improve the phosphorylation level of mTOR, but decrease phosphorylation level of AMPK both in renal tissues of healthy rats and NRK-52E cells." (PMID 33424763, 2020). "Activated Akt induces mTOR activation, leading to suppressed autophagy, while inhibition of mTOR, by rapamycin, ameliorated VC induction, supporting the possibility of a novel mechanistic role of autophagy, in hyperglycemia-related VC." (PMID 32294899, 2020). "Moreover, PHLPP1 down‐regulation plays a crucial role in hyperglycaemia‐induced cardiomyocyte apoptosis via activating the PI3K/AKT/mTOR pathways." (PMID 32150791, 2020). "Acute hyperglycemia could inhibit mitophagy through AMPK/mTOR pathway, which would aggravate mitochondria damage and renal tubular impairment." (PMID 33424763, 2020). "Acute hyperglycemia could enhance ischemic brain damage though mTOR pathway activation, which could be relieved by mTOR inhibitor rapamycin." (PMID 33424763, 2020). "Acute hyperglycemia could inhibit mitophagy through AMPK/mTOR pathway, which would aggravate damaged mitochondria accumulation and renal tubular injuries." (PMID 33424763, 2020).
Hyperglycemia (continued). "The increased LD storage due to hyperglycaemia was partially abolished by pre‐treatment with the mTOR inhibitor/autophagy inducer Torin‐1, which suggests that activation of autophagy could reduce lipid accumulation." (PMID 30710421, 2019). "It is likely that suppression of neuronal PI3K/Akt/mTOR pathway occurs in STZ-induced type 2 DM that may play a role in the pathobiology of hyperglycemia and neurodegeneration and dementia seen in type 2 DM." (PMID 30041644, 2018). "Our results suggest that tau hyperphosphorylation and the sustained over-activated mTOR signalling under hyperglycemia may be due to the suppression of Cav-1." (PMID 28489581, 2017). "Taken together, it suggests that the decline of cognitive function in DM is triggered by hyperglycemia, the process of cognitive dysfunction is contributed by suppressed Cav-1 expression, over-activated mTOR/S6K signalling, and/or the formation of tau hyperphosphorylation." (PMID 28489581, 2017). "Hyperglycemia and hyperlipidaemia are class effects of mTOR inhibition." (PMID 27287020, 2016). "In addition to its role in controlling cancer development, mTOR also contributes to hyperglycemia and hyperlipidmia." (PMID 26115086, 2015). "Therefore, one of the great challenges in cancer therapy with the inhibitors of PI3K/Akt/mTOR would be the subsequent development of hyperglycemia, hyperlipidemia and other metabolic disorders." (PMID 25334061, 2014). "It has been suggested that the hypertrophic changes induced by hyperglycaemia may be the consequence of mTOR activation through autocrine TGF-β signalling." (PMID 26464852, 2014). "In the phase III study in RCC, the most common everolimus-related adverse events were anemia and metabolic abnormalities, including hyperglycemia and hyperlipidemia, which are considered to be the result of inhibition of mTOR-regulated glucose and lipid metabolism." (PMID 21232120, 2011). "However, the consequent cytoplasmatic hyperglycemia causes an overactive mTOR/S6, leading to a negative feedback loop in the IGFR/InsR intracellular signaling (IR at cellular level)." (PMID 40277891, 2025). "Additionally, phenolic compounds such as anthocyanins can exert the oxidative stress on islet cells against hyperglycemia through the AMPK/ACC/mTOR pathway, as well as cyanidin-3-glucoside protected cells from high glucose-induced oxidative stress by activating glutathione synthesis." (PMID 39199254, 2024). "In addition, hyperglycemia was also demonstrated to promote macrophage pyroptosis and pro-inflammatory factor secretion by activating mTOR/4EBP1 and decreasing downstream ULK1 activity and autophagy flux, which in turn, aggravates alveolar bone resorption in periodontitis." (PMID 37298150, 2023). "Mammalian target of rapamycin (mTOR) inhibitors have attained significant attention in the field of oncology and exhibit a wide range of toxic effects like headache, mucositis, rashes, and metabolic toxicities including hyperglycemia, hyperlipidemia, and hypophosphatemia." (PMID 37513916, 2023). "Thus, the current study not only describes the mechanisms of neurodegeneration through hyperglycemia-/mTOR/autophagy/apoptosis pathway, but also provides a rationale for the development of new strategies based on autophagy modulation to manage neuronal cell death in the early period of DR." (PMID 33637094, 2021). "Thus, the inhibition of mTOR or RhoA/ROCK in glomerular endothelial cells may represent a novel therapeutic strategy for preventing hyperglycemia-induced albuminuria." (PMID 34627341, 2021). "Furthermore, the management of hyperglycemia could restore the mTOR activity, inhibit autophagy and prevent neuronal cell death." (PMID 33637094, 2021). "Moreover, our results indicated that GQL in T2DM treatment may affect the TNF/NF-κB and PI3K/AKT/MTOR pathways to reduce inflammation and improve hyperglycemia." (PMID 34381354, 2021).
Hyperglycemia (continued). "Moreover, severe effects are associated with the inhibition of (mammalian target of rapamycin) (mTOR)-regulated pathways, such as immunosuppression, dyslipidemia, and hyperglycemia due to nonspecific biodistribution after the oral administration of Rapa." (PMID 33916918, 2021). "It has also been reported that hyperglycemia promotes the proliferation of malignant BC epithelial cells by increasing activity of the leptin/insulin-like growth factor-1 receptor signaling pathway and causing activation of the Protein Kinase B/mechanistic target of rapamycin (AKT/mTOR) pathway." (PMID 33718202, 2021). "We hypothesize that this may be explained by the fact that chronic exposure to moderately elevated BCAA values added to hyperglycemia or pro-inflammatory conditions could decrease the threshold of mTOR phosphorylation and increase reactive oxygen species (ROS) formation." (PMID 34684308, 2021). "The reduction in CTLA-4+ Tregs in hyperglycemia coincided with a metabolic shift marked by decreased GLUT1 expression and overall downregulation of mTOR phosphorylation." (PMID 41597269, 2026). "Peripheral hyperglycemia-induced LPA upregulates Arf6-driven macropinocytosis of fucosylated CD147+ LG-EVs, which activates AKT/mTOR/4EBP1 signaling to promote SFR." (PMID 41362734, 2026). "Hyperglycaemia and insulin excess potentiate leptin-mediated signalling, particularly via IGF1R–Akt–mTOR activation, further accelerating cell cycle progression and biomass accumulation in breast and mammary epithelial cells." (PMID 41586225, 2025). "This study investigates the impact of maternal hyperglycemia on hippocampal morphology and autophagy‐related gene expression in neonates by focusing on the AKT/PI3K/mTOR pathway." (PMID 40660790, 2025). "Maternal hyperglycemia disrupts hippocampal development by altering autophagy and activating the PI3K/mTOR pathway, contributing to neuronal damage." (PMID 40660790, 2025). "Hyperglycemia also augments insulin and insulin-like growth factor (IGF-1) signaling, activating the PI3K/AKT/mTOR pathway, which enhances cellular proliferation, survival, and angiogenesis while suppressing antitumor immune surveillance." (PMID 41479778, 2025). "Under the acute hyperglycemia conditions induced by STZ injection, human tau enhanced Akt and mTOR activation." (PMID 40054691, 2025). "After identifying the PI3K/mTOR pathway as a therapeutic vulnerability, they treated DIPG-bearing mice with paxalisib and saw responses but also observed hyperglycemia as a severe side effect." (PMID 38488006, 2024). "Adiponectin prevents the loss of telomerase activity and premature vascular senescence during hyperglycemia by activation of AMPK/TSC2/mTOR/S6K1 signaling and inhibition of PI3K/Akt/mTOR/S6K1 signaling." (PMID 39063184, 2024). "mTOR inhibition via systemic administration of RAPA also has been shown to suppress VEGF expression and retinal oxidative stress response to hyperglycemia in murine models." (PMID 37240765, 2023). "In hyperglycemia, the autophagy promoted by AMPK phosphorylation and mTOR inhibition partially rescued the compromised BMSCs osteogenic differentiation, and the downregulation of autophagy led to opposite outcomes." (PMID 37298150, 2023). "Common AEs related to sapanisertib across all schedules in both phases included hyperglycemia, nausea, and vomiting, which are all well-known side effect of PI3K/mTOR pathway inhibition." (PMID 37072571, 2023). "In contrast, our study with diabetic tree shrews demonstrated that diabetic retinas experience the elevation of TRIB3 and p-AKT/AKT→ p-mTOR/mTOR signaling, whereas the IRS level at 16 weeks of hyperglycemia was reduced." (PMID 35163410, 2022). "Hyperinsulinemia and hyperglycemia lead to alterations of VIC activation, differentiation and matrix remodeling as well as to an abrogation of mTOR phosphorylation." (PMID 36386326, 2022).
Hyperglycemia (continued). "The expression of NT5DC3 declined significantly during hyperglycemia, while that of other proteins, such as p-PI3K, p-AKT, p-mTOR, IL-1β, and TNF-α, was substantially higher." (PMID 36553697, 2022). "Hyperglycemia inhibits AMPK, which in turn activates mTOR, but ketosis activates AMPK and inhibits mTOR." (PMID 34579079, 2021). "Firstly, we have recently reported that chronic hyperglycemia induces over-expression of DNMT1 and subsequent aberrant DNA methylation of multiple regulator genes of the mechanistic target of rapamycin (mTOR) in peripheral blood mononuclear cells (PBMCs)." (PMID 33737884, 2021). "ROS was activated, mitochondrial membrane potential and LC3-II/LC3-I ratio were decreased but P62 and BNIP3L/Nix were increased in hyperglycemia groups (P < 0.05), which were reversed by AMPK activation or mTOR inhibition." (PMID 33424763, 2020). "The activation of the mTOR and Jak/STAT pathways, and the higher expression levels of pepck and pomc genes, contributed to the anorexia with the enhanced hyperglycemia." (PMID 32636801, 2020). "Hyperglycemia promotes breast cancer progression by altering leptin/IGFR1 and Akt/mTOR signaling, whereas, in pancreatic cancer, it contributes to ROS stimulated cancer progression via suppression of the JNK and c-Jun pathways." (PMID 31546918, 2019). "Hyperglycaemia promotes expression and release of VEGF 39, 40, which activates the PI3K/Akt/mTOR signalling pathway." (PMID 29377505, 2018). "Hyperglycaemia, a known on-target effect of PI3K-Akt-mTOR inhibitors, was observed as early as 4 h after dosing and decreased toward the baseline level at 24 h." (PMID 29795308, 2018). "Hyperglycemia impairs autophagy in HUVECs through inhibition of the phosphorylation of AMPK, activating the downstream effector mTOR through mTOR phosphorylation and leading to endothelial cell damage." (PMID 28503253, 2017). "Collectively, hyperglycemia-induced TXNIP contributes to the dysregulation of tubular autophagy and mitophagy in diabetic nephropathy through activation of the mTOR signaling pathway." (PMID 27381856, 2016). "mTOR inhibition with CCI-779 has shown dysregulation of glucose and lipid metabolism leading to side effects like hyperglycemia, hypophosphatemia, anemia, and hypertriglyceridemia in patients." (PMID 29083380, 2016). "Hyperglycemia due to the ad libitum diet in the 19AL group resulted in an autophagy level similar to that of the 19S group through decreased AMPK and increased mTOR phosphorylation." (PMID 26060824, 2015). "We found that acute hyperglycemia prevents VMH GI neurons from producing NO and depolarizing in response to decreased glucose as a result of mTOR inhibition of AMPK." (PMID 25540613, 2014). "In order to determine the effects of hyperglycemia on signaling events further downstream, we assessed activation of AKT/mTOR." (PMID 24260287, 2013). "Hyperglycemia resulted in activation of AKT and mTOR as early as 24 hr in MCF7 and MDA-231 cells and this effect was sustained through 72 hr." (PMID 24260287, 2013). "As described in the study with rapamycin and Akt inhibitor, GSK690693, inhibition of the mTOR pathway may increase insulin resistance and possibly reduce β-cell function, necessitating vigilant glucose monitoring and active intervention to control hyperglycaemia." (PMID 22343617, 2012). "Hyperglycemia triggers podocyte apoptosis through pathways involving ROS, renin-angiotensin system (RAS), mammalian target of rapamycin (mTOR), and transforming growth factor-beta/SMAD (TGF-β/SMAD) signaling pathway, contributing to podocyte loss and albuminuria in DKD." (PMID 39941397, 2025). "This may be attributed to the fact that hyperglycemia activates the insulin-like growth factor-1 (IGF-1) and PI3K/AKT/mTOR pro-survival signaling pathways, thereby enhancing the resistance of tumor cells to treatment." (PMID 41357588, 2025).
Hyperglycemia (continued). "The findings demonstrated that maternal hyperglycemia induces hippocampal volume reduction, increased neuronal damage, and dysregulated autophagy‐related gene expression, particularly through the activation of the PI3K/mTOR pathway." (PMID 40660790, 2025). "Furthermore, hyperglycemia plays a role in promoting breast cancer progression by changing leptin/IGFR1 and Akt/mTOR signaling." (PMID 39410536, 2024). "Studies found that diabetic cognitive dysfunction is related to mTOR signaling pathway, and activation of PI3K/Akt/mTOR signaling pathway can improve nerve defects in diabetic cerebral ischemia reperfusion rats and hyperglycemia induced neurotoxicity of PC-12 cells." (PMID 36348200, 2023). "Finally, miR-7 mimics can reduce the mTOR levels through the PI3K/AKT/mTOR signaling pathway and thereby reduce hyperglycemia-induced damage in RPECs, which indicates that it is a potential therapeutic strategy for the prevention and treatment of DR." (PMID 37978169, 2023). "The results indicated that NT5DC3 efficiently suppressed the development of T2D to colorectal tumors in BALB/c mice, while NT5DC3 protein expression declined during hyperglycemia, and LF inhibited this malignant progression by regulating the levels of NT5DC3 and the PI3K/AKT/mTOR signaling pathways." (PMID 36553697, 2022). "In conclusion, our findings from in vivo and in vitro experiments showed that the mTOR inhibitor, rapamycin, blocks the up-regulation of VEGF and GFAP in the diabetic rat retina and also inhibits the hyperglycemia-induced increase in ROS in cultured Müller cells and HERMCs." (PMID 33479328, 2021). "Likewise, NEAT1 is a lncRNA which shows its elevated expression in hyperglycemia and has been shown to directly interfere AKT/mTOR signalling pathway." (PMID 34742256, 2021). "Hyperglycemia triggers intracellular pathways, which promote tumor progression, such as increased leptin levels and pro-cell survival AKT/mTOR, enhancement of WNT/βcatenin signaling, induction of epithelial mesenchymal transition and upregulation of inflammatory cytokine levels in circulation." (PMID 33212778, 2020). "First, healthy elderly people chronically treated with rapamycin or other mTOR inhibitors showed no ill effects (e.g. hyperglycemia)." (PMID 31586989, 2019). "This picture is further complicated by feedback systems in responsive metabolic systems; hyperglycemia resulting from inhibition of PI3K is corrected through increased insulin secretion which, in turn, activates PI3K/mTOR signaling, reducing the impact of the primary PI3K inhibition." (PMID 31443495, 2019). "SOM230 is an FDA-approved drug (in 2012, for the treatment of Cushing's pituitary tumours) that, despite inducing hyperglycaemia, does not generate any toxicity, unlike translation mTOR inhibitors such as RAD001 (Everolimus® Novartis)." (PMID 25834145, 2015). "Exogenous H2S can induce/enhance autophagy to inhibit the proliferation of colon epithelial cells or reduce hyperglycemia-induced matrix remodeling by glomerular endothelial cells via signaling pathways of AMP-activated protein kinase (AMPK) and mammalian target of rapamycin (mTOR)." (PMID 26078809, 2015). "In addition, metformin, an agent that controls hyperglycemia in DM, activates AMPK and inhibits mTOR activity to promote autophagy and cytoprotection." (PMID 26064426, 2015). "Other important observations from this study include enhanced IGF1R signaling and increased AKT/mTOR activation under hyperglycemia in both non-tumorigenic and malignant breast epithelial cells." (PMID 24260287, 2013). "In MCF10A cells, AKT phosphorylation was not increased under hyperglycemia until 72 hr, but mTOR phosphorylation was increased at both 24 hr and 72 hr." (PMID 24260287, 2013).